Y_RNA (Y RNA )
Gene: Miscellaneous RNA gene on chromosome 3 (75,964,980 to 75,965,069, reverse strand). Ensembl gene ENSG00000222883.
Homologues: Orthologues: chimpanzee Y_RNA (100% identical), guinea pig Y_RNA (80% identical), dog Y_RNA (76% identical), pig Y_RNA (73% identical). Paralogues in human: Y_RNA (82% identical), RNY3 (81% identical), Y_RNA (81% identical), Y_RNA (80% identical), RNY3P1 (79% identical), RNY3P2 (79% identical), Y_RNA (79% identical), RNY3P9 (78% identical), Y_RNA (78% identical), RNY3P14 (77% identical), RNY3P4 (77% identical), Y_RNA (77% identical), and 84 more.